CHRM1 (cholinergic receptor muscarinic 1)
Diseases named in the same sentence as CHRM1 in open-access papers (continued):
Sharing a sentence is not in itself a finding about the gene and the disease.
schizophrenia (continued). "However, with the recognition that the breakdown of biochemical homeostasis in people with schizophrenia extends beyond the CNS some consideration should be given as to whether CHRM1 / CHRM4-mediated biochemical abnormalities in people with the disorder could extend beyond the CNS." (PMID 36909280, 2023). "Understanding the mechanisms causing lower levels of cortical [3H]pirenzepine binding has been advanced by studies showing lower levels of CHRM1 gene expression and protein in the DFPLC of people with schizophrenia." (PMID 36909280, 2023). "Chrm1, which was decreased in FASD female pups, is altered in the cortex of ASD and schizophrenia patients." (PMID 35268026, 2022). "Although both studies support lower levels of CHRM1/CHRM4 in people with schizophrenia, neither of the studies were sufficiently powered to identify the MRDS subgroup identified using postmortem CNS." (PMID 36909280, 2023). "One of these studies also reported lower levels CHRM4, but not CHRM1, mRNA across the hippocampus from people with schizophrenia compared to controls." (PMID 36909280, 2023). "Importantly, biperiden is a selective CHRM1/CHRM4 antagonist (10-fold more selective for CHRM1 over CHRM4) that is known to induce significant deficits in learning and memory in both patients with schizophrenia and controls." (PMID 36909280, 2023). "For example, the CHRM1 and CHRM3 have been shown to be important in odor discrimination and learning, a deficit that has been demonstrated in people with schizophrenia." (PMID 36909280, 2023). "Hence, current data would argue that changes in CHRM1 in the cortex, but not necessarily other CNS regions, are a significant component of the molecular pathology of schizophrenia." (PMID 36909280, 2023). "Postmortem and neuroimaging studies show low levels of cortical muscarinic M1 receptors (CHRM1) in patients with schizophrenia which is significant because CHRM signalling has been shown to change levels of gene expression and cortical gene expression is altered in schizophrenia." (PMID 34521861, 2021). "However, levels of CHRM1 mRNA were not different between schizophrenia cases with CHRM1 deficits compared to those with normal levels of CHRM1 protein." (PMID 29657307, 2018). "These trials included phase II and III trials showing the efficacy of KarXT, which is predicted to having its therapeutic benefits from the inclusion of CHRM1/CHRM4 dual agonism, against the positive and negative symptoms of schizophrenia." (PMID 36909280, 2023). "In the striatum, it has been reported that levels of [3H]pirenzepine binding but not CHRM1 or CHRM2 mRNA, were lower in people with schizophrenia compared to controls." (PMID 36909280, 2023). "When considering the breakdown in cholinergic homeostasis in schizophrenia it is significant that people with MRDS and non-MRDS have lower levels of CHRM1-expressing pyramidal cells in laminae III and V of the DLPFC." (PMID 36909280, 2023). "In addition, changes in CHRM1, but not CHRM2/4, signaling has been reported in the DFPLC in people with schizophrenia." (PMID 36909280, 2023). "Moreover, neither study quantified CHRM1/CHRM4 in the hippocampus, a region important in modulating learning and memory which have shown impairments in people with schizophrenia." (PMID 36909280, 2023).
Alzheimer disease (10 papers, 2013 to 2025). A progressive, neurodegenerative disease characterized by loss of function and death of nerve cells in several areas of the brain leading to loss of cognitive function such as memory and language. "The findings provide novel mechanistic insights into Chrm1 loss with the appearance of mitochondrial pathophysiological deficits in Alzheimer’s disease." (PMID 37274741, 2023). "We found that CHRM1 (having putative G4/iMs in first 500 bp upstream), CYP27C1 and FOXH1 (having putative G4/iMs in their first 200 bp upstream) are all linked to pathways related to Alzheimer’s disease." (PMID 31597270, 2019). "Interestingly, elucidating the role of the cholinergic system in the etiology of psychosis has been aided by studies into Alzheimer's disease where the CHRM1/CHRM4 partial agonist Xanomeline can reduce psychotic symptoms." (PMID 23805071, 2013). "Post-mortem studies have also reported reduced binding of the radioligand [3H]4-DAMP, under CHRM1/CHRM3/CHRM4/CHRM5 selective assay conditions, in the orbitofrontal cortex from subjects with Alzheimer's disease who had significant psychotic symptoms." (PMID 23805071, 2013).
colon cancer (10 papers, 2014 to 2025). "Linear regression results for the expression levels of CHRM1 and genes commonly mutated in colon cancer." (PMID 35370785, 2022). "To identify pathways associated with downregulated CHRM1 expression in colon cancer we performed a Gene Ontology (GO) analysis on the 5,776 gene subset which also had an adjusted p-value of ≤ 0.01 and had available KEGG data (3,921 genes)." (PMID 35370785, 2022). "Notably, in mice with combined Chrm1/M1R and Chrm3/M3R deficiency, M1R deficiency outweighs the effects of M3R deficiency; that is mice with combined M1R and M3R deficiency have as many colon tumors as control mice." (PMID 35370785, 2022). "While we anticipated detecting genes previously implicated in colon cancer, the relative relationship to changes in CHRM1 expression suggests a common relationship between the concurrent changes observed in CHRM1 and APC/CTNNB1, and these downstream β-catenin target genes." (PMID 35370785, 2022). "In contrast, HCT116 cells, expressed higher relative levels of CHRM1 mRNA, thus providing us with experimental colon cancer cell lines with a broad range of relative expression of CHRM1 and CHRM3 for our studies." (PMID 37835460, 2023). "Analysis of the UALCAN dataset revealed that CHRM1 transcript levels were approximately 30% lower in colon cancer compared to a normal colon [0.316 versus 1.03 transcripts per million, respectively (p = 0.044)]." (PMID 37835460, 2023). "Collectively, these findings support the finding of increased CHRM3 expression but reduced CHRM1 expression in colon cancer." (PMID 37835460, 2023). "First, while CHRM1 gene expression was modestly but significantly reduced in colon cancer compared to normal tissue, M1R protein expression levels were significantly increased in both colon adenomas and adenocarcinomas compared to a normal colon." (PMID 37835460, 2023). "In contrast, we found that CHRM1 mRNA expression is significantly reduced in human colon neoplasia and Chrm1 ablation in mouse models negates the anti-neoplastic effects of Chrm3 ablation; that is, Chrm1/M1R expression appears to protect against colon cancer." (PMID 37835460, 2023). "In contrast, CHRM1 transcript levels in the same dataset were modestly, but significantly (p = 0.044), reduced in colon cancer compared to a normal colon." (PMID 37835460, 2023). "Further, we identified an imperfect but linear relationship between CHRM1 and APC and CTNNB1 mRNA levels, supporting a relationship between CHRM1/M1R and β-catenin signaling in colon cancer." (PMID 35370785, 2022). "Knockout of M1 muscarinic receptor (CHRM1) in azomethane-treated mice can reduce the number and size of colon cancer." (PMID 35250903, 2021). "That is, concomitant genetic ablation of Chrm1 in Chrm3-/- mice appeared to mitigate reductions in both colon tumor number and volume that we repeatedly observed in AOM-treated Chrm3-/- compared to WT mice." (PMID 24694019, 2014). "However, little was reported regarding CHRM1 expression in colon cancer or relative CHRM1 versus CHRM3 expression." (PMID 37835460, 2023). "Moreover, CHRM1 transcript levels in colon cancer were significantly lower than CHRM3 transcript levels (p < 0.0005)." (PMID 37835460, 2023). "In summary, we have demonstrated a novel anti-proliferative effect of M1R activation in human colon cancer cells that may explain why CHRM1/M1R levels in colon cancer are relatively reduced compared to CHRM3/M3R levels." (PMID 37835460, 2023). "Gene Ontology analysis applied across all genes associated with CHRM1 suggested the effects of CHRM1 downregulation in colon cancer are not subtle, supporting a conceptual framework in which CHRM1 plays a protective role against colon cancer development." (PMID 35370785, 2022). "In WT, Chrm1-/- and dual KO mice the majority of colon tumors were adenocarcinomas." (PMID 24694019, 2014).
colon cancer (continued). "We also confirmed the absence of compensatory increases in Chrm3 expression in Chrm1-/- mice that could account for the Chrm1-/- colon tumor phenotype." (PMID 24694019, 2014). "In mouse models of colon cancer, Chrm1/M1R deficiency does not reduce tumor size or number." (PMID 35370785, 2022). "This concept was again supported in the present work by our interrogation of a large public colon cancer database which confirmed that while CHRM3 levels were significantly elevated in cancer compared to those in normal colon tissue, CHRM1 levels were modestly, but significantly, reduced in cancer." (PMID 37835460, 2023). "This further validates that CHRM1/M1R downregulation observed in colon cancer is not only non-random, but very likely involved in important aspects of development and/or progression of disease." (PMID 35370785, 2022). "As β-catenin is a target of phosphorylation by PKA, which is activated by cAMP, reduced expression of CHRM1/M1R in colon cancer would attenuate β-catenin signaling mediated by this non-canonical M1R/cAMP/PKA/β-catenin axis." (PMID 35370785, 2022). "We reasoned that genes whose expression levels were different in tumors from Chrm3-/- compared to WT mice, but not in tumors from Chrm1-/- compared to WT mice, would more likely be relevant to M3R-induced colon tumor promotion." (PMID 24694019, 2014). "We were surprised to observe that genetic ablation of Chrm1 did not alter the number or volume of colon tumors in Chrm1-/- mice compared to WT mice." (PMID 24694019, 2014). "To explore the relative expression of M1R and M3R in established human colon cancer cells, we selected three commonly used cell lines to examine the relative expression of CHRM1 and CHRM3 mRNA; HT-29, H508, and HCT116 cells were used in many of our in vitro studies of colon cancer cell function." (PMID 37835460, 2023). "Whereas, in azoxymethane-treated mice, ablating CHRM3 expression attenuates colon neoplasia, ablating CHRM1 did not significantly alter colon tumor number or size and, surprisingly, may have trended towards promoting colon neoplasia." (PMID 33450835, 2021). "Here, to explore the individual roles and interplay between two muscarinic receptor subtypes, we analyzed systematically the effects of Chrm3 and Chrm1 gene ablation, alone and in combination, on AOM-induced murine colon neoplasia, a model closely resembling non-hereditary human colon cancer." (PMID 24694019, 2014).
prostate carcinoma (10 papers, 2016 to 2026). A carcinoma that arises from epithelial cells of the prostate gland. "In this line, other studies have also reported that CHRM1 is involved in regulating the migration and invasion of prostate cancer through the Hedgehog signaling pathway." (PMID 37347365, 2023). "In human prostate cancer cell lines and mouse models of prostate cancer, cholinergic signals are transduced in the tumor stroma through the muscarinic cholinergic receptor 1 (CHRM1) to promote tumor invasion." (PMID 37347365, 2023). "A recent study reported that nerve ending-derived acetylcholine induces CHRM1 activation in mesenchymal cells to promote prostate cancer invasion and metastasis." (PMID 33398073, 2021). "Autonomic nerve system-mediated prostate cancer progression occurs through activation of CHRM1 signaling." (PMID 33398073, 2021). "Cholinergic signaling promotes tumor invasion and metastasis in mouse models of prostate cancer, the inhibition of which can be achieved by pharmacologic blockade or genetic disruption of the Type 1 cholinergic muscarinic receptor (CHRM1)." (PMID 33322770, 2020). "CHRM1 has been shown to have an effect on prostate cancer in a high-impact article with 56 citations to date, although it was published in 2013." (PMID 27112211, 2016). "Among them, Fatty Acid Synthase (FASN) exhibited the best diagnostic performance in the TCGA validation cohort (AUC = 0.800), outperforming PTGS2 (0.783), ENPP2 (0.621), and CHRM1 (0.605), and was significantly overexpressed in prostate cancer tissues (|log2FC| > 1, adjusted P < 0.05)." (PMID 42228706, 2026). "However, CHRM1 seems to be much involved in prostate cancer." (PMID 27112211, 2016). "Since we showed that upregulated NGF cannot increase expression of CHRM1 and CHRM3, this result suggests that NGF–CHRM4 might be a unique signaling pathway involved in neuroendocrine differentiation of prostate cancer that differs from canonical acetylcholine–CHRM pathways." (PMID 33398073, 2021).
Cognitive impairment (8 papers, 2019 to 2025). Abnormal cognition is characterized by deficits in thinking, reasoning, or remembering. "CHRM1 was regarded as the main target because 32 essential oil compositions could act on CHRM1 and be highly associated with cognitive impairment and chronic obstructive pulmonary disease." (PMID 35702766, 2023). "This pathway may have some clinical significance, as it is suggested that through this process CHRM1 activation could rescue β-amyloid mediated cognitive impairment, is an important pathophysiological process associated with Alzheimer’s disease." (PMID 36909280, 2023). "Oleamide is a documented neuroactive fatty-acid amide that reverses scopolamine-induced cognitive impairment and restores cholinergic function, which aligns with its moderate docking to ACHE/CHRM1 in our dataset and the enrichment of synaptic receptor pathways." (PMID 41440909, 2025). "Surprisingly, Chrm1−/− mice displayed no significant cognitive impairments in contextual fear conditioning or the Morris water maze, a test that is frequently used to assess spatial reference memory in rodents." (PMID 37293125, 2023).
depression (5 papers, 2017 to 2025). "Β- caryophyllene and dibutyl phthalate could directly act on CHRM1, FAAH, CNR2, SLC6A2, and SLC6A3, which were associated with anesthesia, attention deficit hyperactivity disorder, and major depressive disorder." (PMID 40729010, 2025).
pancreatic cancer (4 papers, 2020 to 2024). "However, intriguingly, in pancreatic cancer, the activation of CHRM1 can inhibit the growth and migration of tumor cells." (PMID 38567163, 2024).
asthma (3 papers, 2023). "Some studies also found that CHRM1 was associated with bronchoconstriction of the airways, asthma, nicotine dependence and chronic obstructive pulmonary disease." (PMID 35702766, 2023). "COPD-associated eQTLs target cholinergic pathway genes (e.g., CHRM1 and CHRM3) that have previously been implicated as important susceptibility loci for lung diseases (e.g., asthma and COPD)." (PMID 36574990, 2023). "In the case of chronic obstructive pulmonary disease, it is significant that the CHRM1–/– mouse has changes in bronchoconstriction and a pan-CHRM1, 2 and 3 antagonist is used to treat asthma." (PMID 36909280, 2023).
colon adenocarcinoma (3 papers, 2022 to 2023). "We found CHRM1 levels were downregulated in colon adenocarcinoma, while, as expected, CHRM3 was upregulated." (PMID 35370785, 2022).
glioma (3 papers, 2022 to 2025). A benign or malignant brain and spinal cord tumor that arises from glial cells (astrocytes, oligodendrocytes, ependymal cells). "We found that HRH1 and CHRM3 were expressed at higher levels in GBM (grade IV) in comparison to lower-grade gliomas (grade II and III), while CHRM1 displayed the opposite trend." (PMID 37760589, 2023). "While not the most highly expressed cholinergic receptor gene in glioma, CHRM1 seems to play a unique role in OPC-like DMG cells, distinguishing it from other CNS tumor entities such as glioblastoma, ependymoma, and medulloblastoma." (PMID 40541184, 2025). "Electrophysiology may also help determine whether additional receptor subunits beyond CHRM1 and CHRM3 contribute to putative cholinergic glioma synapses." (PMID 40541184, 2025). "The identification of a high number of immune processes with the CHRM1, CHRM3 and GRIN-1 neurotransmission-related gene signature may suggest that NT-related gliomas possess distinct tumor immune microenvironments." (PMID 35455749, 2022). "Correlations between the CHRM1, CHRM3 and GRIN-1 NT-1-4 glioma intersecting gene signatures and various immune signaling pathways suggested that NT gliomas may be endowed with distinct tumor immune microenvironments." (PMID 35455749, 2022). "The well-established antagonist activity of clemastine against H1R and the inhibitory effects of M1R and M3R signaling on oligodendrocyte differentiation prompted us to determine the expression profiles of these three receptor genes (HRH1, CHRM1, and CHRM3) in gliomas." (PMID 37760589, 2023). "To look into the regulation of specific cellular signaling pathways by neurotransmitter-related genes in glioma, we performed a correlation analysis of the TCGA glioma dataset between previously-identified NT1-4 discriminatory genes (CHRM1, CHRM3 and GRIN1) and non-neurotransmission-related genes." (PMID 35455749, 2022).
adenoma (2 papers, 2014 to 2023). A neoplasm arising from the epithelium. "In contrast, apoptotic cells were not significantly different in adenomas from Chrm1-/- and WT mice." (PMID 24694019, 2014). "Compared to adenomas from AOM-treated WT mice, Ki67 staining was significantly reduced in those from Chrm3-/- and dual KO but not Chrm1-/- mice." (PMID 24694019, 2014).
Anxiety (2 papers, 2019 to 2021). Intense feelings of nervousness, tension, or panic often arise in response to interpersonal stresses. "We observe significant enrichment of NTSR2, GPR88 and Gabrg1 in chloroquine-activated neurons, and relatively lower expression of OPRM1, PENK and Chrm1, suggesting that these genes could be critical candidates in regulating pruritis and its associated anxiety." (PMID 34032210, 2021).
colorectal adenocarcinoma (2 papers, 2022 to 2023). The most common type of colorectal carcinoma. "In an unbiased analysis, we found that in contrast to CHRM3, expression of CHRM1 was significantly downregulated in human colorectal adenocarcinomas." (PMID 37835460, 2023). "Collectively, these patterns of changes in gene expression levels and cancer-related pathways support a conceptual framework wherein CHRM1/M1R expression contributes to protection against the development and progression of colorectal adenocarcinoma." (PMID 35370785, 2022). "We detected a consistent pattern of CHRM1 downregulation across colorectal adenocarcinomas." (PMID 35370785, 2022).
memory impairment (2 papers, 2022 to 2024). "There are reports on the critical role of CHRM1 in memory impairment, and a decrease in its density is associated with learning and memory disorder, and cognition dysfunction." (PMID 35109845, 2022).
migraine (2 papers, 2024). "For example, DrugBank annotates 14 drugs as targeting CHRM1, and this list include anticholinergics, neuroleptics, migraine treatments, and ophthalmological preparations." (PMID 38736684, 2024).
Sepsis (2 papers, 2017 to 2021). Sepsis is defined as life-threatening organ dysfunction caused by a dysregulated host response to infection. "The expression of the gene encoding the M1 mAChR receptor, Chrm1 was decreased in the hippocampus of mouse sepsis survivors (n = 8 per group)." (PMID 29326685, 2017).
cognitive decline (1 paper, 2023). "This implies that hippocampal loss of Chrm1 may not lead to cognitive decline, but a cortical loss of Chrm1 may harm cognitive function." (PMID 37293125, 2023).